MBD1 (methyl-CpG binding domain protein 1)
Description:
Transcriptional repressor that binds CpG islands in promoters where the DNA is methylated at position 5 of cytosine within CpG dinucleotides. Binding is abolished by the presence of 7-mG that is produced by DNA damage by methylmethanesulfonate (MMS). Acts as transcriptional repressor and plays a role in gene silencing by recruiting ATF7IP, which in turn recruits factors such as the histone methyltransferase SETDB1. Probably forms a complex with SETDB1 and ATF7IP that represses transcription and couples DNA methylation and histone 'Lys-9' trimethylation. Isoform 1 and isoform 2 can also repress transcription from unmethylated promoters.
Synonyms: CXXC3; PCM1; RFT
Tractability: PROTAC: UniProt records ubiquitination sites on it; ubiquitination databases record sites on it; its protein half-life has been measured.
Gene: Protein-coding gene on chromosome 18 (50,266,746 to 50,281,846, reverse strand). Ensembl gene ENSG00000141644.
Subcellular location: Nucleus; Nucleus matrix; Nucleus speckle; Chromosome
Subcellular location (Human Protein Atlas): Nucleoplasm; Vesicles
Pathways (Reactome):
Metabolism of proteins: SUMOylation of transcription cofactors
Gene Ontology:
Molecular function: double-stranded methylated DNA binding; methyl-CpG binding; protein binding; unmethylated CpG binding; zinc ion binding; DNA binding; chromatin binding
Biological process: DNA methylation-dependent constitutive heterochromatin formation; negative regulation of DNA-templated transcription; negative regulation of transcription by RNA polymerase II; transcription by RNA polymerase II; epigenetic regulation of gene expression; negative regulation of astrocyte differentiation; negative regulation of gene expression; neuron differentiation; response to bisphenol A; response to cocaine; response to estradiol; response to nutrient levels; response to xenobiotic stimulus; ventricular cardiac muscle tissue development
Cellular component: chromosome; nuclear matrix; nuclear speck; nucleoplasm; nucleus; chromatin
Genetic constraint (gnomAD): Loss-of-function variants: 25 observed, 85.17 expected, observed/expected ratio (o/e) 0.29, 90% interval 0.21 to 0.41. The upper end of that interval is the gene's LOEUF score, 0.41, which puts it in group 1 of 6, group 1 being the genes least tolerant of losing a copy. Missense variants: 627 observed, 853.03 expected, observed/expected ratio (o/e) 0.74, 90% interval 0.69 to 0.79. Synonymous variants: 301 observed, 317.77 expected, observed/expected ratio (o/e) 0.95, 90% interval 0.86 to 1.04.
Homologues: Orthologues: chimpanzee MBD1 (99% identical), macaque MBD1 (99% identical), pig MBD1 (87% identical), dog MBD1 (86% identical), rabbit MBD1 (84% identical), guinea pig MBD1 (76% identical), mouse Mbd1 (71% identical), rat Mbd1 (68% identical), tropical clawed frog mbd1 (34% identical), zebrafish mbd1b (22% identical), Drosophila melanogaster MBD-like (10% identical). Paralogues in human: MBD3 (15% identical), MBD2 (15% identical), MBD3L1 (7% identical), MBD3L2 (7% identical), MBD3L2B (7% identical), MBD3L3 (7% identical), MBD3L4 (7% identical), MBD3L5 (7% identical).
Diseases named in the same sentence as MBD1 in open-access papers:
MBD1 is named in the same sentence as 42 diseases in open-access papers, as found by Europe PMC text mining. Sharing a sentence is not in itself a finding about the gene and the disease. The quoted sentences say what the papers report.
pancreatic cancer (10 papers, 2008 to 2024). "The present study combined a proteomic approach with RNAi technology to identify proteins associated with MBD1 function in pancreatic cancer." (PMID 18445260, 2008). "Our data suggest that these differential proteins may be associated with the function of MBD1, and provide some insight into the functional mechanism of MBD1 in the development of pancreatic cancer." (PMID 18445260, 2008). "These differential proteins may be associated with the function of MBD1, our findings provide some insight into the functional mechanism of MBD1 in the development of pancreatic cancer." (PMID 18445260, 2008). "MBD1, a key player in transcriptional regulation and genomic stability, is significantly upregulated in pancreatic cancer tissues compared to adjacent normal tissues, which correlates with lymph node metastasis and poor patient survival." (PMID 39682281, 2024). "The course of pancreatic cancer also relies on methyl-CpG binding domain protein 1 (MBD1), which, when upregulated, correlates with lymph node metastasis and poor prognosis for patients." (PMID 35745656, 2022). "Significantly, targeting MBD1 reverses the EMT phenotype of pancreatic cancer and restores sensitivity to chemotherapy." (PMID 30761005, 2019). "When MBD1 expression was knocked down in vitro, pancreatic cancer cell growth was inhibited and apoptosis was induced." (PMID 31516389, 2019). "In a recent study, MBD1 (methyl-CpG-binding domain protein 1), a protein highly expressed in pancreatic cancer, was found to downmodulate KEAP1 expression by influencing the methylation status of its promoter." (PMID 31097977, 2019). "Previous study reported that the upregulation of MBD1 enhanced the epithelial mesenchymal transition and invasion of pancreatic cancer cells, which suggested that MBD1 contributed to the tumor growth in pancreatic cancer." (PMID 28473981, 2017). "To investigate the changes in protein expression in pancreatic cancer after MBD1 knock-down, we performed a comparative proteomic study between BxPC-3/MBD1-siRNA and BxPC-3/vector cell lines." (PMID 18445260, 2008). "Our data provide some insight into the functional mechanism of MBD1 in the development of pancreatic cancer." (PMID 18445260, 2008). "In this study, we silenced MBD1 expression in the pancreatic cancer cell line BxPC-3 using the RNA interference (RNAi) technique." (PMID 18445260, 2008). "In this study, we established a MBD1-knock-down pancreatic cancer cell line (BxPC-3) using stable RNA interference, to compare the proteomic changes between control and MBD1-knock-down cells using two-dimensional gel electrophoresis and mass spectrometry." (PMID 18445260, 2008). "We successfully used RNAi technology to construct a recombinant MBD1-siRNA plasmid that stably knocked-down MBD1 gene expression in the BxPC-3 human pancreatic cancer cell line." (PMID 18445260, 2008). "We have previously reported that MBD1 is over-expressed in human pancreatic carcinomas and that over-expression of MBD1 correlated significantly with lymph node metastasis." (PMID 18445260, 2008). "Previously, we have shown that the gene expression of MBD1 is significantly increased in pancreatic carcinomas compared to normal pancreatic tissue, with a simultaneous decrease in the expression of some tumor suppressor genes (CDH1, RB)." (PMID 18445260, 2008). "We also found that the protein and mRNA expressions of MBD1 in pancreatic carcinoma were significantly higher than in normal tissues." (PMID 18445260, 2008). "MBD1 increases pancreatic cancer therapy resistance through DNA repair." (PMID 32469064, 2020). "MBD1 inhibition obstructs pancreatic cancer cell invasion and EMT via E-cadherin down-regulation." (PMID 32469064, 2020). "In addition, methyl-CpG binding domain protein 1 (MBD1) has an important function in pancreatic cancer, where it is upregulated and correlates with lymph node metastasis and poor survival." (PMID 30761005, 2019).
pancreatic cancer (continued). "Interestingly, previous studies by our team also found high expression of MBD1 in pancreatic cancer cell lines and tissues." (PMID 31516389, 2019). "Interestingly, the delivery of RNA interference of MBD1 into pancreatic cancer cells in vitro by poly(d,l-lactic-co-glycolic acid) (PLGA)-poloxamer nanoparticles had been tested and showed a good therapeutic effect." (PMID 25751725, 2015). "Indeed, in pancreatic cancer (PC), knocking down MBD1 using small interfering RNA (siRNA) would dramatically inhibit cell growth and invasion, induce apoptosis, as well as increase the sensitivity of cells to radiation and cisplatin." (PMID 25751725, 2015). "In this study, the down-regulation of both GRP78 and HSP A8 after MBD1 knock-down, suggest that MBD1 may affect the expression of HSPs in pancreatic cancer through DNA methylation." (PMID 18445260, 2008). "In the short term RNAi experiment, the mRNA level of vimentin was also down-regulated after MBD1 knock-down, indicated that MBD1 may involve in DNA methylation of vimentin and mediate the expression of vimentin in pancreatic cancer." (PMID 18445260, 2008). "Down-regulation of these tumor-related proteins after MBD1-knock-down suggests that MBD1 may play a significant role in pancreatic cancer through regulating methylation." (PMID 18445260, 2008). "We established a MBD1 knock-down BxPC-3 pancreatic cancer cell line using a stable RNAi method." (PMID 18445260, 2008). "Over-expression of MBD1 has been reported in human pancreatic carcinomas." (PMID 18445260, 2008). "In pancreatic cancer, the transcriptional silencing of SIRT3 by zinc finger E-box binding homeobox-1 (ZEB1) in cooperation with the methyl-CpG-binding domain protein 1 (MBD1) promotes a metabolic shift towards glycolysis." (PMID 39682281, 2024). "Previous studies have demonstrated that MBD1 may contribute to tumorigenesis by binding to hypermethylated CpG islands in the promoters of tumor suppressor genes in cancer cells, for example, in pancreatic cancer, lung cancer, prostate cancer and leukemia cells." (PMID 31516389, 2019). "However, the role of MBD1 during the development of pancreatic cancer is still unknown." (PMID 18445260, 2008). "However, the role of MBD1 in the development of pancreatic cancer is still unknown." (PMID 18445260, 2008).
lymph node metastasis (5 papers, 2008 to 2022). "Furthermore, the expression of MBD1 correlated with lymph node metastasis." (PMID 18445260, 2008).
colon cancer (4 papers, 2018 to 2023). "On the other hand, we have found that MBD1 loss is a frequent event in colon carcinogenesis, being associated with descending colon tumors in different studies." (PMID 29755661, 2018). "STAT1 binds to the IRF promoter region in colon cancer cells, while MBD1 inhibits IRF8 expression, which is another indication evidence that WT1 in leukemia and IRF8 are anticorrelated." (PMID 37250717, 2023). "Similarly, we found the expression of MBD1 and MBD2 was upregulated in MSI colon cancer patients, implying both regulators might involve in immune activation." (PMID 36276973, 2022).
lung carcinoma (4 papers, 2015 to 2019). "Mutation analyses revealed that a number of mutations occurred in the MBD1 gene in colon and lung cancer cell lines, indicating a suppressor role of MBD1 in human tumorigenesis." (PMID 25751725, 2015). "Moreover, polymorphisms in the MBD1 gene have shown an association with the increased risk of developing lung cancer." (PMID 31245293, 2019). "Previous studies demonstrated that the polymorphism of MBD1 was related to the risk of lung cancer, which provided evidence that MBD1 might inhibit tumor growth in lung cancer." (PMID 28473981, 2017).
prostate carcinoma (4 papers, 2015 to 2019). A carcinoma that arises from epithelial cells of the prostate gland. "mRNA expression profiling showed that the expression of the vast majority of genes in both control and MBD1-deletion prostate cancer cells remained unchanged." (PMID 25751725, 2015). "Moreover, analysis of patient biopsies revealed that the MBD1 protein expression gradually decreased with the increase of prostate cancer grade." (PMID 31245293, 2019). "In prostate cancer cells, depletion of MBD1 increased cell invasion with no change in apoptosis compared to control cells where MBD1 expression was intact." (PMID 31245293, 2019).
autism (3 papers, 2014 to 2025). Persistent deficits in social interaction and communication and interaction as well as a markedly restricted repertoire of activity and interest as well as repetitive patterns of behavior. "Similarly, the RNA of the epigenetic regulator MBD1, whose deficiency is linked to autism-related behaviors in mice, was also among the altered ASD risk genes." (PMID 40470213, 2025). "Since the serotonin system was reported to relate to autism, the regulation of MBD1 on Htr2c is likely to contribute to autism." (PMID 25751725, 2015). "Because the MBD1-miRNA regulatory system has been indicated to be important for neural stem cell fate determination, studying this system can extend the knowledge of normal brain development and allow the search for specific miRNAs as therapeutic candidates for brain diseases, such as autism." (PMID 25751725, 2015).
breast carcinoma (3 papers, 2015 to 2024). "Several genes found on chromosome 18, such as SMAD4, SMAD2, MIB1, and MBD1, are involved in breast cancer development and progression." (PMID 38803515, 2024).
gastric cancer (3 papers, 2016 to 2022). A primary or metastatic malignant neoplasm involving the stomach. "We have demonstrated that MBD1 promoted the progression of gastric cancer by recruiting HDAC3 to form a complex, silencing the expression of anti-tumor miR-5701, and increasing the expression of the miR-5701 targets FGFR2." (PMID 35876658, 2022).
glioma (3 papers, 2022 to 2025). A benign or malignant brain and spinal cord tumor that arises from glial cells (astrocytes, oligodendrocytes, ependymal cells). "Conversely, a small decrease in the expression of an MBD1 isoform containing exon 12 was predicted in the IDH-mutant glioma." (PMID 37372972, 2023). "Specifically, in the case of MBD1, we found that the splicing index of exon 10 was increased in the IDH-mutant glioma (mean PSI: 0.31) compared to IDH-WT (mean PSI: 0.13), indicating the higher expression of an MBD1 isoform containing this exon in the IDH-mutant glioma." (PMID 37372972, 2023).
autoimmune disease (2 papers, 2014 to 2022). A disorder resulting from loss of function or tissue destruction of an organ or multiple organs, arising from humoral or cellular immune responses of the individual to their own tissue constituents. "Athymic nude mice that received MBD1-deficient thymus develop autoimmune diseases, indicating that thymic MBD1 may provide a protective effect against the development of autoimmune disease." (PMID 36110862, 2022). "Notably, ATF7IP’s repressive partners MBD1 and SETDB1 have very different knockout phenotypes, namely mild spatial learning defects and autoimmune disease in adult mice lacking Mbd1, and early embryonic lethality at 3.5 to 5.5 days post conception for the Setdb1 deletion." (PMID 25028596, 2014).
Candida infection (2 papers, 2011 to 2021). "The modulation of mBD1 in the vaginal mucosa in response to Candida infection suggests an active role of this AMP during AVVC." (PMID 35049960, 2021). "In contrast to murine beta-defensin 1 (mBD1), which was not induced following infection in any of the mice, mBD2, -3, -and 4 all showed elevated expression in oral tissues following Candida infection in WT mice." (PMID 22174673, 2011).
cervical cancer (2 papers, 2020 to 2023). A primary or metastatic malignant neoplasm involving the cervix. "It was verified that the expression of MBD1 was prominently increased in cervical cancer cells compared with normal cervical cells." (PMID 32469064, 2020). "In the end, rescue assays unveiled that NR2F2-AS1 enhanced the development of cervical cancer through miR-4429/MBD1 axis." (PMID 32469064, 2020). "According to the results above, we draw a conclusion that NR2F2-AS1 promotes the progression of cervical cancer via targeting miR-4429/MBD1 axis." (PMID 32469064, 2020). "Rescue experiments confirmed that MBD1 overexpression partly rescued NR2F2-AS1 knockdown-mediated inhibition of progression in cervical cancer." (PMID 32469064, 2020). "In summary, our work firstly illuminated that NR2F2-AS1 contributed to the development of cervical cancer via sponging miR-4429 to regulate MBD1, which may be beneficial to cervical cancer treatment in the future." (PMID 32469064, 2020). "Our results showed that NR2F2-AS1 accelerated cervical cancer progression through sponging miR-4429 to modulate methyl-CpG-binding domain protein 1 (MBD1), which may promote the development of therapeutic strategies of cervical cancer." (PMID 32469064, 2020). "Furthermore, we found that the mRNA and protein expression of MBD1 were declined by miR-4429 mimics transfected cervical cancer cells in qRT-PCR and Western blot." (PMID 32469064, 2020). "Moreover, NR2F2-AS1 acted as a molecular sponge of miR-4429 and methyl-CpG-binding domain protein 1 (MBD1) was a downstream target of miR-4429 in cervical cancer." (PMID 32469064, 2020). "MBD1 was hereby speculated as the target gene of miR-4429 in cervical cancer." (PMID 32469064, 2020). "Finally, we demonstrated whether NR2F2-AS1 promoted the progression of cervical cancer by targeting miR-4429/MBD1 axis." (PMID 32469064, 2020). "MBD1 up-regulation reversed the inhibitory effects of NR2F2-AS1 knockdown on the proliferation, colony formation of cervical cancer cells, but counteracted the elevated percentage of apoptotic cells resulted from NR2F2-AS1 knockdown." (PMID 32469064, 2020). "Further, our study confirmed that MBD1 interacted with miR-4429 cervical cancer and NR2F2-AS1 up-regulated MBD1 by competing for miR-4429 in cervical cancer." (PMID 32469064, 2020).